PRPF3 (pre-mRNA processing factor 3)
Description:
Plays a role in pre-mRNA splicing as component of the U4/U6-U5 tri-snRNP complex that is involved in spliceosome assembly, and as component of the precatalytic spliceosome (spliceosome B complex).
Synonyms: hPrp3; PRP3; SNRNP90; HPRP3P; Prp3p; RP18
Tractability: Small molecule: a structure with a bound ligand is known; it has a binding pocket of medium quality. PROTAC: UniProt records ubiquitination sites on it; ubiquitination databases record sites on it; its protein half-life has been measured.
Gene: Protein-coding gene on chromosome 1 (150,321,479 to 150,353,233, forward strand). Ensembl gene ENSG00000117360.
Subcellular location: Nucleus; Nucleus speckle
Subcellular location (Human Protein Atlas): Nucleoplasm
Pathways (Reactome):
Metabolism of RNA: mRNA Splicing - Major Pathway
Gene Ontology:
Molecular function: identical protein binding; protein binding; RNA binding
Biological process: mRNA splicing, via spliceosome; spliceosomal tri-snRNP complex assembly; mRNA processing; RNA splicing; RNA splicing, via transesterification reactions; spliceosomal complex assembly; spliceosomal snRNP assembly; spliceosome conformational change to release U4 (or U4atac) and U1 (or U11)
Cellular component: Cajal body; nucleoplasm; nucleus; precatalytic spliceosome; spliceosomal complex; U12-type precatalytic spliceosome; U2-type precatalytic spliceosome; U4/U6 x U5 tri-snRNP complex; U4 snRNP; U4/U6 snRNP; U4atac snRNP; U4atac/U6atac snRNP; U4atac/U6atac x U5 tri-snRNP complex; nuclear speck; protein-containing complex
Genetic constraint (gnomAD): Loss-of-function variants: 3 observed, 89.13 expected, observed/expected ratio (o/e) 0.0337, 90% interval 0.014 to 0.087. The upper end of that interval is the gene's LOEUF score, 0.087, which puts it in group 1 of 6, group 1 being the genes least tolerant of losing a copy. Missense variants: 463 observed, 866.33 expected, observed/expected ratio (o/e) 0.53, 90% interval 0.49 to 0.58. Synonymous variants: 270 observed, 304.43 expected, observed/expected ratio (o/e) 0.89, 90% interval 0.8 to 0.98.
Gene-disease validity (ClinGen):
ClinGen rates the evidence that PRPF3 causes each of these diseases.
retinitis pigmentosa 18 (autosomal dominant): Definitive.
Homologues: Orthologues: chimpanzee PRPF3 (100% identical), rabbit PRPF3 (100% identical), guinea pig PRPF3 (99% identical), mouse Prpf3 (99% identical), rat Prpf3 (99% identical), macaque PRPF3 (93% identical), dog PRPF3 (86% identical), pig PRPF3 (86% identical), tropical clawed frog prpf3 (83% identical), zebrafish prpf3 (75% identical), Drosophila melanogaster Prp3 (45% identical), Caenorhabditis elegans prp-3 (34% identical).
Diseases named in the same sentence as PRPF3 in open-access papers:
PRPF3 is named in the same sentence as 43 diseases in open-access papers, as found by Europe PMC text mining. Sharing a sentence is not in itself a finding about the gene and the disease. The quoted sentences say what the papers report.
retinitis pigmentosa (12 papers, 2010 to 2024). Retinitis pigmentosa (RP) is an inherited retinal dystrophy leading to progressive loss of the photoreceptors and retinal pigment epithelium and resulting in blindness usually after several decades. "Retinitis pigmentosa is also caused by mutations in components of the splicing machinery, such as U4/U6 small nuclear ribonucleoprotein Prp3 (PRPF3), PRPF8, and PRPF31, suggesting a considerable role of RNA biology in this disease." (PMID 26520658, 2015). "Mutations in genes from the same family (PRPF3, 8, and 31) have been implicated in retinitis pigmentosa." (PMID 20126641, 2010). "As the second and third PE targets, we chose PRPF3 and PRPF8 associated with autosomal dominant (ad) forms of retinitis pigmentosa (RP)." (PMID 39795970, 2024). "Mutations in genes encoding the splicing factors PRPF3, PRPF8, PRPF31, RP9, and SNRNP200 can cause non-syndromic retinitis pigmentosa, a severe form of inherited blindness leading to rod photoreceptor degeneration." (PMID 26985665, 2016). "Mutations in six spliceosomal proteins, PRPF3, PRPF4, PRPF6, PRPF8, PRPF31 and SNRNP200, cause retinitis pigmentosa (RP), a disease characterized by progressive photoreceptor degeneration." (PMID 25383878, 2014). "Two previous studies of the effects of mutations in three splicing factors (PRPF3, PRPF8 and PRPF31) linked to retinitis pigmentosa on mRNA splicing in lymphoblast cells reported evidence of retained introns." (PMID 24969741, 2014).
autosomal dominant retinitis pigmentosa (10 papers, 2008 to 2022). Autosomal dominant retinitis pigmentosa (RP) is an autosomally dominant inherited retinal dystrophy leading to progressive loss of the photoreceptors and retinal pigment epithelium and resulting in blindness usually after several decades. "Previous studies reported that PRPF3 and PRPF3 mutations are associated with autosomal dominant retinitis pigmentosa in Chinese individuals." (PMID 35260078, 2022). "A mutation in the PRPF3 gene is rare compared to other genes causing autosomal dominant retinitis pigmentosa (ADRP)." (PMID 20309403, 2010). "An example are mutations in the PRPF3 gene causing a tissue-specific phenotype of autosomal dominant retinitis pigmentosa although PRPF3 is an element of the ubiquitously expressed RNA splicing machinery." (PMID 18596911, 2008). "At least six different proteins of the spliceosome, including PRPF3, PRPF4, PRPF6, PRPF8, PRPF31, and SNRNP200, are mutated in autosomal dominant retinitis pigmentosa (adRP)." (PMID 30967900, 2019).
hepatocellular carcinoma (3 papers, 2020 to 2022). A malignant tumor that arises from hepatocytes. "PRPF3 was reported to be a potential prognostic indicator in hepatocellular carcinoma and promoted the cell growth, migration, and invasion of keratinocyte-derived cutaneous squamous cell carcinoma via the JAK2/STAT3 pathway." (PMID 35260078, 2022). "For example, high expression levels of PRPF3 and SNRPB2 were observed in hepatocellular carcinoma and related to poor prognosis." (PMID 35923625, 2022). "However, the biological role of PRPF3 in hepatocellular carcinoma (HCC) remains to be determined." (PMID 31926109, 2020).
retinal degeneration (3 papers, 2011 to 2021). Degeneration of the retina. "Heterozygous mice with one copy of the PRPF3 or PRPF31 genes knocked out do not cause retinal degeneration." (PMID 21283520, 2011).
pancreatic cancer (2 papers, 2022 to 2023). "We further assessed the effect of TMEM43 via regulating PRPF3/RAP2B axis on pancreatic cancer cell growth in vivo." (PMID 35260078, 2022). "TMEM43 mediates the RAP2B/ERK pathway by binding to and stabilizing PRPF3 to promote pancreatic cancer progression." (PMID 35260078, 2022). "Collectively, these results suggest that TMEM43 mediates pancreatic cancer progression through the PRPF3/RAP2B/ERK signaling pathway." (PMID 35260078, 2022). "To explore the function of PRPF3 in pancreatic cancer, we first established stable PRPF3 knockdown in MIAPaCa-2 and SW1990 cell lines." (PMID 35260078, 2022). "Confocal immunofluorescence assays demonstrated that TMEM43 and PRPF3 colocalized in pancreatic cancer cell cytoplasm." (PMID 35260078, 2022). "Together, our findings suggest that PRPF3 promotes pancreatic cancer (PC) progression via the RAP2B/ERK axis." (PMID 35260078, 2022). "Receiver operating characteristic (ROC) curve analysis suggested that TMEM43, PRPF3, and RAP2B had good diagnostic value in pancreatic cancer patients according to their prognostic value in the GSE62452, GSE16515, GSE28735, and GSE15471 datasets." (PMID 35260078, 2022). "TMEM43 promotes migration and invasion through the PRPF3/RAP2B/ERK axis in pancreatic cancer." (PMID 37367036, 2023). "Moreover, we demonstrated that the protein expression levels of RAP2B and phosphorylated ERK were decreased in PRPF3-silenced pancreatic cancer cells." (PMID 35260078, 2022). "In addition, PRPF3 mRNA levels were significantly positively correlated with RAP2B mRNA levels using the GSE71729 dataset of pancreatic cancer." (PMID 35260078, 2022). "Moreover, we demonstrated that TMEM43 promoted pancreatic cancer progression by stabilizing PRPF3 and regulating the RAP2B/ERK axis." (PMID 35260078, 2022). "In keeping with this, we confirmed that the expression of PRPF3 was significantly elevated in pancreatic cancer samples compared with the control group, signifying that it may play an oncogenic role in pancreatic cancer." (PMID 35260078, 2022). "To confirm that PRPF3 promoted pancreatic cancer progression via RAP2B, we overexpressed RAP2B in PRPF3-silenced SW1990 cells, and found that RAP2B overexpressing rescued RAP2B and p-ERK protein levels." (PMID 35260078, 2022). "Our study shows that the TMEM43/PRPF3/RAP2B/ERK axis plays a vital role in regulating cancer progression, and has a potential clinical application value for pancreatic cancer." (PMID 35260078, 2022). "We demonstrated that PRPF3 knockdown could significantly inhibit cell growth, migration, invasion, and the RAP2B/ERK signaling pathway in pancreatic cancer." (PMID 35260078, 2022). "The present study suggests that TMEM43 contributes to pancreatic cancer progression through the PRPF3/RAP2B/ERK axis, and might be a novel therapeutic target for pancreatic cancer." (PMID 35260078, 2022).
retinal disease (2 papers, 2008 to 2024). "To test the PE technology in hiPSCs with relevance to retinal disease, we chose three IRD genes with ubiquitous expression but associated with an isolated retinal phenotype NMNAT1, PRPF3, and PRPF8." (PMID 39795970, 2024). "Three genes were chosen from a group of human retinal disease genes: C3 (already included), dystrophin, muscular dystrophy (DMD) and PRP3 pre-mRNA processing factor 3 (Prpf3)." (PMID 18989387, 2008).
malignant thyroid tumors (1 paper, 2022). "Interestingly, the roles of top-ranked discriminatory proteins such as SNRPB2, PRPF3, and LSM8 in other diseases have been investigated for years, although there is limited evidence about the associations between these molecules and malignant thyroid tumors." (PMID 35923625, 2022).
night blindness (1 paper, 2010). Inability to see clearly in dim light. "Only one patient carrying a mutation in PRPF3 has been examined in the Spanish family and was described as having a mild phenotype with first symptoms (night blindness) at the age of 40." (PMID 20309403, 2010).
cancer (6 papers, 2020 to 2025). A tumor composed of atypical neoplastic, often pleomorphic cells that invade other tissues. "The correlations between PRPF3 and cancer immune infiltrates were investigated via Tumor Immune Estimation Resource (TIMER)." (PMID 31926109, 2020). "Functional network analysis suggested that PRPF3 regulates spliceosome, DNA replication, and cell cycle signaling via pathways involving several cancer-related kinases and E2F family." (PMID 31926109, 2020). "Among them, PRPF3 has been reported to be an oncogene involved in cancer development." (PMID 35260078, 2022). "Our study reveals a more complex picture in cancer, where chromosomal gains containing various splicing factors (1q gain: SF3B4, PRPF3, 2q gain: CWC22, SF3B1) and other NMD-related genes are associated with reduced NMD efficiency." (PMID 41023738, 2025). "In addition, PRPF3 and MAGOHB have not been linked to cancer before." (PMID 35453681, 2022). "Interestingly, NSF, SF3A3, PRPF3, and MAGOHB have never been studied in cancer." (PMID 35453681, 2022).
tumor (4 papers, 2019 to 2022). "Herein, by tumor purity analysis, the network of PRPF3 alterations is involved in the tumor purity and tumor immunity." (PMID 31926109, 2020). "The results show that PRPF3 expression has significant correlations with tumor purity (r = 0.223, p = 2.90E-05) and significant correlations with the dominant immune cells infiltration levels." (PMID 31926109, 2020). "After the correlation adjustment by tumor purity, the results revealed the PRPF3 expression level was significantly correlated with most immune marker sets of various immune cells in LIHC." (PMID 31926109, 2020). "Moreover, tumor xenografts were also performed to confirm the functions of PRPF3 and RAP2B in vivo, and the results showed that the downregulation of TMEM43, PRPF3, and RAP2B obviously reduced tumor growth in MIAPaCa-2 cells." (PMID 35260078, 2022). "In addition, PRPF3 co-occurrence genes with Log Ratio > 10 also showed the significant correlations with tumor purity and varying degree with immune cells." (PMID 31926109, 2020). "Levels of PRPF3 DNA copy number were significantly higher in tumor tissues than in normal tissue." (PMID 31926109, 2020). "PRPF3 was found up-regulated with amplification in tumor tissues in multiple HCC cohorts." (PMID 31926109, 2020). "Further, our results suggest a potential novel immune regulatory role of PRPF3 in tumor immunity." (PMID 31926109, 2020). "Using multi-dimensional analysis, we evaluated genomic alterations and functional networks related to PRPF3 in HCC and explored its role in tumor immunity." (PMID 31926109, 2020).
neurodevelopmental disorder (1 paper, 2019). A behavioral and cognitive disorder with onset during the developmental period that involves impaired or aberrant development of intellectual, motor, or social functions.
PRPF3 also shares sentences with these, for which no sentence is quoted: cutaneous squamous cell carcinoma (2 papers); infection (2); lung carcinoma (2); acrofacial dysostosis (1); actinic keratosis (1); Allergy (1); Azoospermia (1); bipolar disorder (1); cerebrocostomandibular syndrome (1); craniofacial microsomia (1); cyst (1); diabetes (1); eczema (1); gastric cancer (1); germ cell tumor (1); glomerulosclerosis (1); hearing loss (1); Leber congenital amaurosis (1); major depressive disorder (1); male infertility (1); Marfan syndrome (1); metaphyseal chondrodysplasia (1); muscular dystrophy (1); Nager syndrome (1); neurological disorders (1); periodontitis (1); prion disease (1); renal fibrosis (1); schizophrenia (1); syndromic (1).
A further 2 diseases each share a sentence with PRPF3 in 1 paper.